TUSC2 (tumor suppressor 2, mitochondrial calcium regulator)
Diseases named in the same sentence as TUSC2 in open-access papers (continued):
Sharing a sentence is not in itself a finding about the gene and the disease.
autoimmune disorder (1 paper, 2023). "Since its discovery, TUSC2 has been found to play vital roles in normal immune function, and TUSC2 loss is associated with the development of autoimmune diseases as well as impaired responses within the innate immune system." (PMID 37173921, 2023). "In addition to regulating autoimmune disorder development, TUSC2 has been implicated in the immune response and inflammation in an asbestos-mesothelioma TUSC2-KO mouse study." (PMID 37173921, 2023). "Deceased TUSC2-KO mice frequently showed signs of systemic infection, fibrinoid necrotizing arteritis in multiple organs, severe nephropathy, anemia, and glomerulonephritis, which are pathologies associated with autoimmune disorders such as systemic lupus erythematosus." (PMID 37173921, 2023). "Additionally, TUSC2-KO mice also had high levels of circulating autoreacting nuclear antibodies, further implicating TUSC2 as an important regulator of the immune system and TUSC2 loss as a potential driver of autoimmune disorder development." (PMID 37173921, 2023). "In normal cells, TUSC2 regulates the immune system and prevents the development of autoimmune diseases." (PMID 37173921, 2023). "Overall, TUSC2 functions as an important factor involved in overall immune system regulation through multiple downstream immune related genes, specifically in T, B, and NK cells, controlling the innate immune response and the development of autoimmune disorders." (PMID 37173921, 2023).
bladder cancer (1 paper, 2023). "Additionally, miR-663 was also found to target TUSC2 and to be significantly upregulated in bladder cancer." (PMID 37173921, 2023).
cervical clear cell carcinoma (1 paper, 2023). "Herein, we used comparative analysis to screen out genes with large differences in expression between HPV-negative and HPV-positive cervical clear cell carcinoma patients, including ALKBH7, MYCBP, MZF1, RNF207, RRS1, and TUSC2." (PMID 37654657, 2023).
cognitive deficits (1 paper, 2024). "In this study, we address the Tusc2-dependent brain immune changes that may underlie cognitive impairment, focusing on the early stages of the disease in 4-month-old males and females." (PMID 39000512, 2024). "In our earlier study, we showed that 5-month-old female Tusc2 KO mice have significant cognitive deficits when compared with WT females." (PMID 39000512, 2024). "Thus, we suggest that increased expression of IFN-γ in Th1 cells in the female Tusc2 KO brain, similar to that seen in patients with neurodegenerative diseases, is involved in the development of cognitive impairment." (PMID 39000512, 2024).
head and neck cancer (1 paper, 2023). A primary or metastatic malignant neoplasm affecting the head and neck. "Due to the drastic differences in TUSC2 methylation status between normal and head and neck cancer tissues, TUSC2 is suggested as a potential biomarker for head and neck cancer initiation." (PMID 37173921, 2023). "However, further investigation is necessary to establish TUSC2 methylation as a potential biomarker in head and neck cancers." (PMID 37173921, 2023). "In head and neck cancers, TUSC2 is partially methylated in cancerous tissue." (PMID 37173921, 2023).
hearing loss (1 paper, 2023). "Lastly, TUSC2 loss promotes premature aging with the development of hearing loss and sporadic Alzheimer’s disease." (PMID 37173921, 2023).
hemangioma (1 paper, 2023). A benign vascular lesion characterized by the formation of capillary-sized or cavernous vascular channels. "Additionally, deceased TUSC2-KO mice frequently exhibited spontaneous tumors, including hemangioma, hemangiosarcoma, lymphoma, and other spontaneous malignancies, indicating that TUSC2 loss may play a role in tumorigenesis." (PMID 37173921, 2023).
memory impairment (1 paper, 2024). "Since inflammation, particularly chronic inflammation, is a critical pathology linked to memory impairment, we set out to investigate neuroinflammation in the Tusc2 KO mice of both sexes via analysis of brain immune cells." (PMID 39000512, 2024). "Most importantly, we characterize Tusc2-, age-, and sex-dependent immune changes in the brain of Tusc2 KO mice that may provide new knowledge on the cause of early memory impairment." (PMID 39000512, 2024). "Therefore, we investigated Tusc2-dependent mechanisms of memory impairment in 4-month-old mice, comparing changes in resident and brain-infiltrating immune cells." (PMID 39000512, 2024). "However, an analysis of additional subtypes of microglia related to neurodegeneration will be helpful in understanding if it plays a role in Tusc2-related memory impairment." (PMID 39000512, 2024).
oral cancer (1 paper, 2018). "(C-D) TUSC2P expression is related to TUSC2 in both oral cancer tissues and adjacent normal tissues (n = 49)." (PMID 30219035, 2018). "(A-B) The expression level of TUSC2 and TUSC2P is lower in oral cancer tissues compared with adjacent normal tissues (n = 49)." (PMID 30219035, 2018). "TUSC2 and TUSC2P expression was detected in tumor samples and matched adjacent normal tissue from ESCC patient (n = 56), and then validated in oral cancer samples (n = 49), using qRT-PCR." (PMID 30219035, 2018). "(E-F) Kaplane-Meier survival curves according to the relative expression level of TUSC2 and TUSC2P in 49 oral cancer patients." (PMID 30219035, 2018). "Decreased level of TUSC2 and TUSC2P indicate worse oral cancer prognosis." (PMID 30219035, 2018).
papillary thyroid cancer (1 paper, 2023). "Overexpression of miR-584 in TPC-1 papillary thyroid cancer cells significantly decreases apoptosis and significantly decreases TUSC2 mRNA and protein expression." (PMID 37173921, 2023). "TUSC2 expression is significantly decreased in both anaplastic thyroid carcinoma (ATC) and papillary thyroid cancer cells (PTC) compared to normal thyroid samples." (PMID 37173921, 2023).
small cell carcinoma (1 paper, 2012). A neuroendocrine carcinoma composed of small malignant cells which are often said to resemble "oat cells" under the microscope. "Prudkin and coworkers observed the lowest levels of TUSC2 in small cell carcinomas(SCLC), which are also neuroendocrine in origin." (PMID 22558101, 2012).
thyroid tumour (1 paper, 2020). "We have previously showed a negative association between the expression of TUSC2 and thyroid tumour progression." (PMID 31973107, 2020).
triple-negative breast carcinoma (1 paper, 2019). An invasive breast carcinoma which is negative for expression of estrogen receptor (ER), progesterone receptor (PR), and human epidermal growth factor receptor 2 (HER2). "TUSC2, a tumour suppressor which is directly targeted by miR-138 in the context of triple-negative breast carcinoma, performs similar anti-tumour functions in other cancers." (PMID 31481748, 2019).
tumor (40 papers, 2009 to 2025). "Although TUSC2 elicits tumor suppressive effects, the role of TUSC2 loss in tumorigenesis remains uninvestigated and warrants further research." (PMID 37173921, 2023). "FUS1/TUSC2 overexpression in tumor cells is associated with cell cycle arrest at G1/S and G2/M transition checkpoints." (PMID 35181743, 2022). "On the molecular level, we associated TUSC2 with activation of multiple tumor-suppressor genes, down-regulation of oncogenes, and modulation of numerous immune genes." (PMID 19852844, 2009). "In addition, the reduced TUSC2 mRNA levels were significantly associated with advanced tumor stages (p < 0.0001), the presence of lymph node metastasis (p < 0.0001), and a poorer histological differentiation (p < 0.05)." (PMID 40243558, 2025). "Meraz and his colleagues delivered TUSC2 (tumor suppressor that encodes a multikinase inhibitor and has been shown to be lost in non-small cell lung carcinoma) systemically by nanovesicles, which was shown to mediate tumor regression." (PMID 39796653, 2024). "This suggests that TUSC2 may interact with other oncogenes and tumor suppressors as potential mechanisms that underly TUSC2-mediated tumor suppression across multiple different cancer types." (PMID 37173921, 2023). "Therefore, Fus1/Tusc2 loss links systemic aging to early senescence, geriatric diseases as well as to tumor escape from immunosurveillance." (PMID 35181743, 2022). "Also, myristoylation-deficient FUS1/TUSC2 loses its characteristic mitochondria/ER localization and its abilities to induce apoptosis and suppress tumor cell proliferation in vitro." (PMID 35181743, 2022). "The tumor suppressor gene showed gene expression and alterations in TUSC2-regulated pathways in vitro and in vivo studies for reduced tumor volume in lung cancer (NCT00059605)." (PMID 40860190, 2025). "The TUSC2 (Tumor Suppressor Candidate 2) gene with the highest tumor suppressor activity is located in the same region." (PMID 40428391, 2025). "Immunohistochemical analysis further confirmed that the TUSC2 protein expression was markedly higher in normal intestinal epithelial tissues compared to tumor tissues." (PMID 40243558, 2025). "The expression level of TUSC2 was found to have the strongest proapoptotic activity in NSCLC cells compared to other 3p21.3 tumor-suppressor genes candidates." (PMID 40428391, 2025). "NPRL2 (Nitrogen Permease Regulator-Like 2) is also known as TUSC4, a tumor suppressor gene, located on chromosome 3p21.31 in a cluster with other tumor suppressor genes including TUSC2/FUS1." (PMID 39932765, 2025). "Since the discovery of TUSC2 in 2000, TUSC2 has been shown to play many regulatory and tumor-suppressive roles in normal and cancerous tissues." (PMID 37173921, 2023). "A pro-immune microenvironment in the tumor is modulated by TUSC2, which makes KRAS/LKB1 tumors more sensitive to carboplatin plus pembrolizumab." (PMID 37008041, 2023). "Filling these knowledge gaps is needed to further elucidate the developmental role of TUSC2 in normal tissue, as well as the mechanisms by which TUSC2 functions as a tumor suppressor." (PMID 37173921, 2023). "Along with the multiple roles TUSC2 plays in the normal cell population, TUSC2 also functions as a tumor suppressor in multiple cancer types." (PMID 37173921, 2023). "TUSC2 regulates a wide range of cellular processes, including cell cycle arrest and apoptosis, through inhibition of several kinases and modulation of the tumor microenvironment (TME)." (PMID 35210547, 2022). "In this regard, Fus1/Tusc2 reminds other tumor suppressors (e.g. PTEN, Spry), which prevent cells from over-stimulation by mitogenic signals maintaining their survival and responsiveness to proliferation signals." (PMID 35181743, 2022).
tumor (continued). "The results clearly demonstrate that restoration of TUSC2 expression profoundly enhances KL tumor response to conventional chemo–immunotherapy." (PMID 35210547, 2022). "Low or no protein expression was explained by its reduced half-life in tumor cells due to the loss of myristoylation, a post-translational modification that prevents FUS1/TUSC2 from proteasome-mediated degradation." (PMID 35181743, 2022). "TUSC2 sensitizes KRAS/LKB1 tumors to carboplatin plus pembrolizumab through modulation of the immune contexture towards a pro-immune tumor microenvironment." (PMID 35210547, 2022). "TUSC2 is a tumor suppressor, and TUSC2P represses cell invasion, migration, and colony formation via the TUSC2P/miR-608/TUSC2 axis." (PMID 35387124, 2022). "Upregulation of miR-197 miRNA that increases FUS1/TUSC2 levels and, thus, suppresses tumor metastasis was attributed to the ability of FUS1 to regulate proliferation of human glioblastoma cells." (PMID 35181743, 2022). "Taken together, the result shows that the combination of TUSC2 and pembrolizumab inhibited tumor growth synergistically, a response that was significantly more effective and durable than that of carboplatin plus pembrolizumab." (PMID 35210547, 2022). "In this review, tracing the history of the tumor suppressor Fus1/Tusc2 studies “from bench to bedside”, we discuss what is known of its role in tumor development, inflammation, and aging." (PMID 35181743, 2022). "miR-138 directly targets a suite of pro-apoptotic and tumour suppressive genes, including tumour suppressor candidate 2 (TUSC2)." (PMID 31481748, 2019). "From this finding, we deduce that TUSC2 is a downstream tumour suppressor which is directly repressed by miR-138." (PMID 31481748, 2019). "We also looked at the effects of miR-138 knockdown on TUSC2 in xenograft tumour sections, and observed a clear inverse correlation between miR-138 and TUSC2 expression." (PMID 31481748, 2019). "TUSC2 overexpressing cells, along with the miR-138 knockdown cell line and the control cell line, all successfully establish tumours in mice." (PMID 31481748, 2019). "Previous investigations have indicated that ectopic expression of TUSC2 inhibited cell proliferation, survival, migration, and invasion, and increased tumor cell death." (PMID 30944041, 2019). "Taken together, all this confirms that TUSC2, a potential tumour suppressor, is a direct target, downregulated by miR-138." (PMID 31481748, 2019). "TUSC2 overexpression therefore substantially mimics the phenotype of miR-138 knockdown and prevents tumour growth." (PMID 31481748, 2019). "Exogenous expression of TUSC2 in non-small cell lung carcinoma cells significantly inhibited tumor cell growth by activating the apoptotic protease activating factor 1 (Apaf-1)." (PMID 30219035, 2018). "We previously established Fus1/Tusc2 as a tumor suppressor, immune modulator and regulator of oxidative stress; however, only recently have we started understanding the molecular mechanisms of these activities." (PMID 28351997, 2017). "Restoration of TUSC2 expression in tumor cells significantly inhibited tumor growth and progression in mouse models." (PMID 29296193, 2017). "Here, we showed that overexpression of TUSC2, a unique tumor suppressor, has the potential to sensitize NSCLC to T cell–dependent immunotherapy by altering the tumor microenvironment via PD-L1 downregulation." (PMID 29296193, 2017). "Overexpression of TUSC2 inhibited tumor growth and progression in mouse models, while TUSC2 knockout mice showed an increased frequency of spontaneous cancers." (PMID 27661106, 2016). "Addition of the thioredoxin reductase 1 inhibitor (TXNRD1) auranofin (AF) to NSCLC cells treated with combination of TUSC2 forced expression with erlotinib increased tumor cell apoptosis and inhibited colony formation." (PMID 27845352, 2016). "Restoration of TUSC2 expression significantly inhibits tumor growth and progression in mouse models." (PMID 27845352, 2016).
tumor (continued). "The DC-TUSC2-AF-erlotinib combination inhibited tumor growth more effectively than AF or TUSC2-erlotinib." (PMID 27845352, 2016). "AF, TUSC2, or erlotinib each produced similar tumor cell killing effects, although that of TUSC2 was slightly better." (PMID 27845352, 2016). "We analyzed the effects of TUSC2 re-expression on tumor cell sensitivity to the AKT inhibitor, MK2206, and explored their mutual signaling connections, in vitro and in vivo." (PMID 24146957, 2013). "Taken together, the central and novel finding in the present study demonstrates the efficacy of TUSC2 transfection in enhancing tumor cell sensitivity to MK2206 treatment." (PMID 24146957, 2013). "Posttreatment tumor biopsies 24 hours after intravenous gene therapy administration showed TUSC2 mRNA expression in 7 of the 8 assessable patients and showed elevated levels of protein expression in all 3 patients tested.." (PMID 22558101, 2012). "Expression array studies showed that TUSC2 activates transcription of multiple genes with tumor suppressor properties and down-regulates pro-tumorigenic genes, thus supporting its role as a tumor suppressor." (PMID 19852844, 2009). "To provide insight into the molecular basis of putative TUSC2 tumor suppressor activity in MPM and perform genome-wide analysis of TUSC2 transcriptional effects, we took advantage of human epithelioid MPM H2595 cells produced in our laboratory." (PMID 19852844, 2009). "Current studies have demonstrated that TUSC2 might play a tumor-suppressing role through inducing apoptosis, arresting the G1 cell cycle, and inhibiting proliferation-related kinases, e.g., EGFR, mTOR, and AKT." (PMID 40243558, 2025). "TUSC2 plays a tumor-suppressive role in a range of human malignancies." (PMID 40243558, 2025). "In accordance with the tumor suppression function of TUSC2 in other cancers, in a subsequent paper, it was shown that in TC, this gene hindered cell proliferation and motility and increased sensitivity to apoptosis by stimulating SMAC/DIABLO and CYTOCHROME C proteins." (PMID 39000555, 2024). "Additionally, restoration of TUSC2 expression promotes tumor suppression, eventuating in decreased cell proliferation, stemness, and tumor growth, as well as increased apoptosis." (PMID 37173921, 2023). "This review will focus on the known functions of TUSC2 in normal tissues and the tumor suppressive functions of TUSC2 in multiple cancer types, as well as efforts in developing anti-cancer therapies that focus on restoring or sustaining TUSC2 expression." (PMID 37173921, 2023). "One potential mechanism of TUSC2 mediated GBM tumor suppression may be through the regulation of the anti-apoptotic factor Bcl-xL." (PMID 37173921, 2023). "However, TUSC2 restoration in these cancer types commonly results in decreased cell proliferation, increased apoptosis, and overall reduction in tumor growth." (PMID 37173921, 2023). "TUSC2 overexpression and erlotinib treatment demonstrate an additive effect, suppressing NSCLC both in vitro and in vivo, and co-administration of TUSC2 and erlotinib decreased tumor growth and metastasis, and increased apoptosis compared to controls or single agent treatment." (PMID 37173921, 2023). "In this study, we use a humanized mouse model to show that while carboplatin plus pembrolizumab reduce tumor growth moderately and transiently, the addition of the tumor suppressor gene TUSC2, delivered systemically in nanovesicles, to this combination, eradicates tumors in the majority of animals." (PMID 35210547, 2022). "We found that TUSC2 inhibited tumor growth to the same extent as carboplatin plus pembrolizumab." (PMID 35210547, 2022). "Furthermore, in high-grade human gliomas, such as GBM, miR-197 was targeted and downregulated by downregulated FUS1 (TUSC2, tumor suppressor candidate 2), and downregulated miR-197 acted as a tumor suppressor to increase tumor cell proliferation." (PMID 35606527, 2022).